H19 (H19 imprinted maternally expressed transcript)
Diseases named in the same sentence as H19 in open-access papers (continued):
Sharing a sentence is not in itself a finding about the gene and the disease.
cholestasis (9 papers, 2018 to 2025). Impairment of the bile flow caused by obstruction within the liver, or outside the liver in the bile duct system. "We therefore asked whether loss of H19 suppressed let-7 family expression during cholestasis." (PMID 30778047, 2019). "Corresponding to the induction of H19 in cholestasis, we examined PTBP1 mRNA expression in BA-insulted cells in vitro and found that it was significantly decreased by the treatments with several BAs in MSC cells." (PMID 30778047, 2019). "Cholestasis induces the hepatic long non-coding RNA H19, which promotes the progression of cholestatic liver fibrosis." (PMID 30778047, 2019). "Furthermore, H19-mediated cholestasis involves polypyrimidine tract-binding protein 1 (PTBP1) downregulation and subsequent aberrant let-7 expression, suggesting a multi-layered regulatory network." (PMID 40832105, 2025). "Experimental evidence from the multidrug resistance 2 gene knockout [Mdr2(−)] cholestasis model reveals sex-specific lncRNA H19 overexpression in female mice, where estrogen induces its expression through the extracellular signal-regulated kinase 1/2 signaling pathway." (PMID 40832105, 2025). "However, the mechanistic links between exosomal lncRNA H19 and macrophage-driven inflammation in cholestasis remain unclear." (PMID 31940841, 2020). "However, microRNAs that are dysregulated by H19 during cholestasis remain elusive." (PMID 30778047, 2019). "Next, we examined whether H19 affected PTBP1 expression in BDL-induced cholestasis." (PMID 30778047, 2019). "In this study, we determined the role of H19 and its binding protein PTPB1 in the expression and bioavailability of a cluster of let-7 miRNAs in cholestasis." (PMID 30778047, 2019). "Of particular note, the expression levels of let-7a-5p/7d-5p/7f-5p were markedly elevated in primary hepatocytes isolated from H19-BDL compared to Null-BDL livers, suggesting that H19 activated let-7 family expression in hepatocytes during cholestasis." (PMID 30778047, 2019). "To profile H19-regulated miRNAs in cholestasis, we performed miR-seq in Null-BDL and H19-BDL livers, as well as in sham-operated livers (Null-sham and H19-sham)." (PMID 30778047, 2019). "Taken together, this study revealed for the first time that H19 promoted let-7 expression by decreasing PTBP1’s expression level and its binding to the let-7 precursors in cholestasis." (PMID 30778047, 2019). "Supporting a mechanistic role for SHP in regulating inflammation downstream to FXR, it has been shown that SHP inhibits lncRNA H19, and that SHP degradation by Bcl2 increases H19 expression in models of cholestasis." (PMID 30150987, 2018). "Because H19 overexpression increases the expression of pro-inflammatory mediators, such as CD31cd1, IL-4, and IL-17 producing CD41 and CD81 cells in the liver and spleen, these findings highlight a role for SHP in regulating immune responses, at least in setting of cholestasis." (PMID 30150987, 2018). "We find that H19 significantly induces let-7a-5p/7d-5p/7f-5p in cholestatic mouse livers and facilitates the interactions between PTBP1 and pre-let-7d/pre-let-7–7a-1 in vitro, suggesting that the PTBP1/let-7 miRNAs may be involved in the progression of cholestasis." (PMID 30778047, 2019).
epilepsy (9 papers, 2018 to 2025). A brain disorder characterized by episodes of abnormally increased neuronal discharge resulting in transient episodes of sensory or motor neurological dysfunction, or psychic dysfunction. "We previously demonstrated that H19 was significantly upregulated in the latent period of epilepsy and may be associated with cell proliferation and immune and inflammatory responses." (PMID 29636074, 2018). "Conversely, silencing H19 can inhibit the activation of neuroglial cells induced by epilepsy and reduce the inflammatory response, highlighting its important role in the inflammatory response." (PMID 39976094, 2025). "Vectors carrying H19 (AAV9-H19) or short hairpin RNA targeting H19 (AAV9-shRNA) were delivered in a KA rat model of epilepsy." (PMID 39596149, 2024). "Previous studies have indicated that lncRNA H19 was related to immune and inflammatory response in epilepsy." (PMID 35603469, 2022). "Intra‐amygdala injection of KA‐induced epilepsy models in rats and mice was used for the qPCR analyses of H19 expression." (PMID 32648622, 2020). "In the present study, we explored the expression profiles of lncRNAs in the hippocampus of epileptic rat models and found that H19 was significantly upregulated in the latent period of epilepsy." (PMID 29795132, 2018). "Our findings reveal a novel lncRNA H19-mediated mechanism in seizure-induced glial cell activation and provide a basis for developing lncRNA-based strategies to prevent the development of epilepsy." (PMID 29636074, 2018). "The upregulation of H19 in the latent period of epilepsy is involved in SE-induced neuronal damage by functioning as a competing endogenous RNA to sponge miRNA let-7b in the regulation of cellular apoptosis." (PMID 29795132, 2018). "Furthermore, LncRNA H19 was highly expressed in the latent period of epilepsy, contributing to the apoptosis process of hippocampal neurons by targeting let-7b." (PMID 36278003, 2022). "Long non-coding RNA (lncRNA) H19 has diverse functions depending on physiological or pathological state, and its role in epilepsy is unknown." (PMID 29636074, 2018). "In addition, analyses of H19 expression levels in pilocarpine (Pilo)-induced rat model, as well as KA-induced mouse model further confirmed the high expression of H19 in the latent period of epilepsy." (PMID 29795132, 2018). "Results of pre-clinical studies showed that the expressions of LncRNA H19 and LncRNA X inactive specific transcript (XIST) were up-regulated, while the expressions of LncRNA PVT1, LncRNA CACS2, and LncRNA UCA1 were down-regulated in epilepsy animal or cell models." (PMID 36278003, 2022). "LncRNA H19 contributes to hippocampal glial cell activation via modulation of the JAK/STAT pathway and could be a therapeutic tool to prevent the development of epilepsy." (PMID 29636074, 2018). "However, the biological function of H19 in non-neoplastic CNS diseases including epilepsy remains unknown." (PMID 29636074, 2018). "However, the biological role of H19 in non-neoplastic CNS diseases including epilepsy remains unknown." (PMID 29795132, 2018). "However, the role of H19 in non-neoplastic CNS diseases including epilepsy remains unclear." (PMID 29636074, 2018).
nasopharyngeal carcinoma (9 papers, 2017 to 2024). A carcinoma arising from the nasopharyngeal epithelium. "H19 is abnormally expressed in various human cancers, such as pancreatic cancer, nasopharyngeal cancer, and lung cancer, and is usually associated with cancer progression, metastasis, and poor prognosis." (PMID 33520725, 2020). "H19 is also found to be overexpressed in nasopharyngeal carcinoma (NPC) and to promote NPC cell invasion capacity via E-cadherin silencing and miR-630/EZH2 regulation." (PMID 33123473, 2020). "For example, in nasopharyngeal carcinoma, H19 overexpression is closely related to the poor prognosis of patients." (PMID 33520725, 2020). "Much more generally, H19 was shown to induce an increase of EZH2 levels in nasopharyngeal carcinoma cells, by working as a “sponge” for miR-630, thus sequestering it from its target, EZH2 mRNA." (PMID 29643989, 2018). "H19 is overexpressed in several cancer types and is associated with tumor metastasis, for example, where lncRNA H19 suppresses miR-630, perturbing the inhibition of EZH2 in nasopharyngeal carcinoma." (PMID 28304343, 2017). "In nasopharyngeal carcinoma, long noncoding RNA H19 regulates EZH2 expression by interacting with miR-630 and promoted cell invasion." (PMID 29050269, 2017). "Additionally, by acting as ceRNAs, H19 has been confirmed to regulate the migration, invasion, and metastasis of various tumors, including nasopharyngeal carcinoma, bladder cancer, and breast cancer." (PMID 33520725, 2020). "H19 regulated EZH2 and promoted cell invasion by interacting with miR-630 in nasopharyngeal carcinoma." (PMID 31064820, 2019). "Mechanistically, H19 upregulates the expression of its downstream proto-oncogene HRAS (HRas proto-oncogene, GTPase) by sponging miRNA let-7, thus promoting the carcinogenic activity of HRAS in nasopharyngeal carcinoma." (PMID 33520725, 2020).
pituitary adenomas (9 papers, 2018 to 2025). "Studies have shown that sEV-derived lncRNA H19, miR-149-5p and miR-99a-3p inhibit the progress of pituitary adenoma and hsa-miR-21-5p in pituitary adenoma promotes abnormal bone formation in acromegaly." (PMID 39025906, 2024). "The downregulation of H19 RNA in pituitary adenoma tissues compared with the normal pituitary glands has been revealed." (PMID 37189829, 2023). "Only one research work has characterized the role of H19 in a large group of patients with pituitary adenomas." (PMID 37189829, 2023). "Our results do not correspond with previous studies, where the inhibitory role of H19 in pituitary adenomas was suggested." (PMID 37189829, 2023). "Among these, two studies reported the involvement of the lncRNA H19, an imprinted oncofetal gene, which is aberrantly expressed in cancer tissues, and in pituitary adenomas." (PMID 34484116, 2021). "Here, we report that H19 expression is frequently downregulated in human primary pituitary adenomas and is negatively correlated with tumour progression." (PMID 30397197, 2018). "In this study, we demonstrated that lncRNA H19 acts as a tumour suppressor to inhibit pituitary adenoma growth and progression in vivo and in vitro." (PMID 30397197, 2018). "Here, the authors show that H19 lncRNA is downregulated in pituitary adenomas and H19 is able to impede pituitary tumorigenesis via disruption of 4E-BPB1 and Raptor interaction to inhibit the phosphorylation of 4E-BP1." (PMID 30397197, 2018). "Moreover, the expression of H19 in plasma exosomes of patients with pituitary adenomas was significantly lower than in healthy controls." (PMID 37189829, 2023). "In some studies, the inhibitory role of H19 in pituitary adenomas has been suggested." (PMID 37189829, 2023). "These investigations highlighted the importance of lncRNA H19 to study the invasion capacity of GH-secreting pituitary adenomas but also that it could be used as a potential biomarker of diagnosis and prognosis." (PMID 34484116, 2021). "Overexpression of H19 could suppress the proliferation of pituitary adenoma cells in vitro and their growth in vivo." (PMID 34885097, 2021). "Additionally, H19 has been found to be commonly downregulated in primary pituitary adenoma samples." (PMID 34885097, 2021). "There is a lack of studies comparing tissue or exosomal H19 expression with the whole blood on the subject of pituitary adenomas." (PMID 37189829, 2023).
psoriasis (9 papers, 2017 to 2025). An autoimmune condition characterized by red, well-delineated plaques with silvery scales that are usually on the extensor surfaces and scalp. "H19, which regulates IL−17A expression in psoriasis, is also dysregulated in cardiometabolic diseases." (PMID 37310201, 2023). "We then detected the expression of lncRNA H19 which demonstrated a 0.248121-fold decrease in expression in psoriasis." (PMID 34992498, 2021). "Actually, only CD27-AS1 and H19 were indicated to directly relate to psoriasis, and seven other lncRNAs were indirectly related to psoriasis." (PMID 33879268, 2021). "In our exploration of the role of lncRNA H19 and miR-766-3p in psoriasis, we found that the AKT/mTOR pathway was activated by overexpression of miR-766-3p and that lncRNA H19 lessened the expression of the pathway." (PMID 34992498, 2021). "Furthermore, the downregulation of H19 in psoriasis tissues compared with normal tissues was observed in lncRNA profiling studies." (PMID 29192645, 2017). "Several lncRNAs might act as psoriasis biomarkers and/or therapy targets, such as the IL−22-responsive SPRR2C, psoriasis susceptibility gene PRINS, NF-κB-dependent ANRIL, IL−17A-promoting H19, and the innate immune response-related HOTAIR and MALAT1." (PMID 37310201, 2023). "Conversely, H19, which is significantly downregulated in psoriasis epidermis, reduced the expression of inflammatory cytokines in IL−17A-, IL−22- and M5-induced keratinocyte models, while the addition of miR−766-3p to these cell models attenuated H19 regulation of inflammation." (PMID 37310201, 2023). "For instance, lncRNA H19 and MIR31HG play an essential role in keratinocyte differentiation, indicating the potential function of H19 and MIR31HG in pathogenesis of psoriasis." (PMID 34080300, 2021). "In conclusion, we have established that downregulation of lncRNA H19 promoted the proliferation of keratinocytes and skin inflammation by up-regulating miR-766-3p expression levels and inhibiting activation of S1PR3 through the AKT/mTOR pathway in psoriasis." (PMID 34992498, 2021). "We established that downregulation of lncRNA H19 promoted the proliferation of keratinocytes and skin inflammation by up-regulating miR-766-3p expression levels and inhibiting activation of S1PR3 through the AKT/mTOR pathway in psoriasis." (PMID 34992498, 2021). "LncRNA H19 might serve as a sponge for miR-766-3p to up-regulate S1PR3 levels and regulates the proliferation of keratinocytes and skin inflammation by AKT/mTOR pathway in psoriasis." (PMID 34992498, 2021).
triple-negative breast carcinoma (9 papers, 2018 to 2026). An invasive breast carcinoma which is negative for expression of estrogen receptor (ER), progesterone receptor (PR), and human epidermal growth factor receptor 2 (HER2). "For instance, in triple-negative breast cancer, DDIT4-AS1 and H19 are significantly associated with tumor metastasis, recurrence and chemotherapy resistance." (PMID 41316360, 2025). "This study has provided multiple lines of evidences that the lncRNA H19 promotes cancer progression and modulates the DNA damage response in ER+ and triple-negative breast cancer cells." (PMID 37298108, 2023). "In triple negative breast cancer, H19 expression is significantly higher in paclitaxel-resistant cells than in paclitaxel-sensitive cells, with downregulation of H19 restoring chemo-sensitivity in the resistant cells after mediation of the Akt signaling pathway." (PMID 30619763, 2018). "In triple-negative breast cancer, LINC00273 enhances metastasis and stemness through miRNA sponging, and H19 modulates Wnt signaling by sponging miR-141." (PMID 41614739, 2025). "Furthermore, in triple-negative breast cancer (TNBC) cells MDA-MB-231, ectopic H19 provided resistance to ER stress-induced apoptosis." (PMID 41751794, 2026).
Hyperinsulinemia (8 papers, 2015 to 2022). An increased concentration of insulin in the blood. "Meanwhile, in vitro culture experiments confirmed the effect of insulin stimulation on IGF2/H19 in HepG2 cells, providing a potential explanation for intrauterine hyperinsulinemia directly affecting IGF2/H19 and subsequent impaired glucose metabolism." (PMID 35432202, 2022). "In rodent models, acute hyperinsulinemia downregulated H19 and this was due to increased production of let-7 resulting in H19 destabilisation." (PMID 31590432, 2019). "In this context it is highly intriguing to note that the H19/let-7 axis plays another role in muscle: while let-7 inhibits glucose uptake and promotes glucose intolerance, H19 upregulates insulin receptor in diabetic conditions to increase glucose uptake and is downregulated upon hyperinsulinemia." (PMID 26536864, 2015). "Our results demonstrated that the intrauterine hyperinsulinemia environment has increased hepatic FoxO1 levels and subsequently increased expression of DNMT3A and epigenetic alterations on IGF2/H19 DMRs." (PMID 35432202, 2022). "In conclusion, our study demonstrated that intrauterine hyperinsulinemia increased hepatic FoxO1 levels and contributed to the upregulation of DNMT3A, subsequently inducing the downregulation of IGF2/H19 expression in the liver of GDM-F1 mice." (PMID 35432202, 2022). "Acute hyperinsulinemia enhances the activation of the PI3K/AKT pathway, promoting an increase in the biogenesis of miR-let-7, which binds to H19 for its degradation." (PMID 34298896, 2021). "Moreover, acute hyperinsulinemia downregulated H19 through PI3K/AKT-dependent phosphorylation of the miRNA processing factor KH domain-containing AU-rich element binding protein, which also promotes biogenesis of let-7 to mediate H19 destabilization." (PMID 36555704, 2022). "Nevertheless, let-7 is not only sequestered by H19, but also can destabilize it under hyperinsulinemia conditions (as opposed to the highly stabile status of H19 in normal differentiated muscle); therefore it exerts a negative feedback cycle to repress its negative regulator H19." (PMID 26536864, 2015).
retinoblastoma (8 papers, 2013 to 2025). A malignant tumor that originates in the nuclear layer of the retina. "In retinoblastoma, for instance, the lncRNA H19 binds on seven regions to the miR-17-92 cluster members miR-17, miR-18a, miR-19a, miR-19b, and miR-20a suppressing their activity, and inhibiting cancer progression." (PMID 33392094, 2020). "The results of microarray analysis showed that lncRNAs HOTAIR, CCAT1, DNM3OS, HIF1A‐AS1, MEG3 and 7SK expressions were up‐regulated, and lncRNAs PCAT1, MIR31HG, BCAR4, RRP1B and H19 were down‐regulated within retinoblastoma tissues." (PMID 30030888, 2018). "LncRNAs PVT1, AFAP10AS1, HOTAIR, BANCR, H19, DANCR and LINC00202 were up-regulated in retinoblastoma tissues while MT1JP and BDNF-AS were down-regulated." (PMID 32514246, 2020). "Moreover, an inverse correlation was observed between the expression of retinoblastoma (RB) and H19/miR-675." (PMID 23429271, 2013).